BRD9 (bromodomain containing 9)
Diseases named in the same sentence as BRD9 in open-access papers (continued):
Sharing a sentence is not in itself a finding about the gene and the disease.
cancer (continued). "A prime example is BRD9, which is often amplified in cancers but is also a specific vulnerability in SMARCB1-deficient cancers." (PMID 33941852, 2021). "BRD9 is considered a key factor in the progression of several types of cancer, but the development of new ligands for this protein is not straightforward due to their particular binding modes, which involve the rearrangement of some amino acid side chains." (PMID 34885774, 2021). "Though BRD9 is understudied in PCa, growing interest in the community has recently pointed to a potential role in other cancers." (PMID 34944438, 2021). "In contrast, BRD9 is a bromodomain gene that shows variable dependency scores across different cancer cells." (PMID 34298819, 2021). "Specifically, ACTL6A, SMARCD1, SMARCA4 and BRD9 are among the top upregulated genes in cancers compared with the paired control samples." (PMID 34598711, 2021). "A lot of target genes of miR-140-3p, including RRM2, PD-L1, MAPK and BRD9, can be remarkably suppressed by miR-140-3p in cancer cells through binding to the 3′-untranslated regions (3′ UTRs)." (PMID 34496800, 2021). "We provide some evidence (in two treatment-naïve cohorts) that BRD9 is overexpressed in ERG fusion positive cancers and that ERG expression is very weakly correlated with BRD9 expression." (PMID 34944438, 2021). "More specifically, when combined with BAF47-perturbed cells, depletion of BRD9 led to decreased proliferation in these cancer types." (PMID 33143733, 2020). "Owing to its cell type-specific manner of chromatin targeting, the biological functions of BRD9 in other human cancer cells requires further investigation." (PMID 32908135, 2020). "Due to the essential nature of GBAF under these conditions, the vulnerability of MRT and SS to BRD9 depletion is indirect; i.e., BAF47 deficiency makes these cancers vulnerable to BRD9 inhibition/depletion." (PMID 33143733, 2020). "Previous studies indicate that BRD9 is a subunit of SWI-SNF complexes and is associated with epigenetic changes in cancer cells." (PMID 32908135, 2020). "As a BRD9 degradation molecule was recently reported, it will be of great interest to test its efficacy in RT cancers." (PMID 31015438, 2019). "Consistent with the GBA prediction, knocking down BRD9 expression dramatically inhibited cancer cell growth in vitro." (PMID 30760718, 2019). "For example, the recurrent focal amplification of BRD9 is observed in 9 cancer types and genetic depletion of BRD9 inhibits tumor growth." (PMID 30760718, 2019). "We confirmed BRD9 protein expression in cancers by retrieving the immunohistochemical staining data from the Human Protein Atlas26." (PMID 30760718, 2019). "All of these findings highlight the expansive potential of BRD9 as a therapeutic target in multiple human cancers." (PMID 31504061, 2019). "We ranked the genes whose expression were positively correlated with BRD9 at both the cancer type-specific and pan-cancer levels, then performed gene-set enrichment analysis." (PMID 30760718, 2019). "To perform a clinically relevant analysis, we focused on nine cancer types in which BRD9 is focally amplified." (PMID 30760718, 2019). "To study how the cancer cells were affected by the genetic alteration of BRD9 or ACTL6A, we performed KEGG analysis and GSEA analysis." (PMID 31504061, 2019). "However, since traditional bromodomain inhibitors cannot effectively treat BRD9‐dependent cancers, this target has long been considered an “undruggable” difficult target." (PMID 41049269, 2025). "Notably, several cancer-associated genes are located within a 1 Mb proximity including CLPTM1L, TERT, BRD9, TRIP13, NKD2, LPCAT1, and IRX4." (PMID 40278994, 2025). "Since exon 15 inclusion in BRD9 has been reported to lead to nonsense-mediated decay and lower transcript levels in UVM and MDS, we sought to investigate BRD9 gene expression levels in additional cancer types that harbor SF3B1 mutations." (PMID 39261602, 2024).
cancer (continued). "Finally, Cancer Dependency Map analysis and BRD9 inhibition displayed BRD9 dependency and sensitivity in cell lines and primary CLL cells." (PMID 39261602, 2024). "BRD9 may affect cancer progression through different phosphorylation sites or N6‐methyladenosine site modifications." (PMID 38303608, 2024). "Bromodomain-containing protein 9 (BRD9) is a key player in chromatin remodeling and gene expression regulation, and it is closely associated with the development of various diseases, including cancers." (PMID 39124901, 2024). "To further examine the translational relevance of BRD9 as a candidate therapeutic target, we used freshly isolated primary cancer patient samples and treated them with I-BRD9 or in combination with gemcitabine for 72 hours followed by single-cell RNA-sequencing for ~12,000 cells." (PMID 37739089, 2024). "Although some existing evidence based on cytological or in vivo experiments supported the association between BRD9 and some specific cancers, there has been no reported comprehensive analysis for BRD9 in pan‐cancer." (PMID 38303608, 2024). "Recent studies have indicated that inhibition of BRD9 may have potential value in the treatment of certain cancers." (PMID 39124901, 2024). "Therefore, it is highly necessary to probe the molecular mechanism of orthosteric and allosteric regulations on BRD9’s activity for the development of anti-cancer drugs targeting BRD9." (PMID 39124901, 2024). "Dysregulation may lead to uncontrolled growth of cancer cells since they often exploit the gene regulation function of BRD9." (PMID 39162964, 2024). "Therefore, since BRD9 is overexpressed in several types of cancer and involved in the dysregulation of gene expression, inhibiting BRD9 aims to interfere with the processes that promote cancer development and progression." (PMID 38543178, 2024). "With the previous correlations in mind, this would suggest that m6A regulators could affect tumour progression in different cancer types by regulating BRD9 expression." (PMID 38303608, 2024). "ncBAF was reported to regulate pluripotency in mouse ES cells, and the Brd9 component of ncBAF was required for pigment specific gene expression during melanocyte differentiation, but little else is known outside the context of cancer." (PMID 37511016, 2023). "The connection of BRD9 with PI3K pathway, miR RNAs, and STAT5 is implicated in cancer progression." (PMID 35883603, 2022). "Overexpression of BRD9 has been found in some cancers such as cervical cancer." (PMID 35702041, 2022). "Furthermore, the connection of BRD9 with the PI3K pathway, microRNAs, and STAT5 is implicated in cancer progression." (PMID 36289829, 2022). "BRD9 also is involved in DNA replication, DNA repair, and cellular responses to DNA damage; thus, targeting BRD9 provides opportunities for new avenues in cancer treatment." (PMID 36297001, 2022). "Both RNA interference (RNAi)-mediated BRD9 knockdown and CRISPR-Cas9-mediated BRD9 knockout compromised the proliferation of SMARCB1-mutant MRT cells, providing compelling support that BRD9 is a therapeutic target for SMARCB1-mutated cancers." (PMID 34298819, 2021). "The biological function of BRD9 is also unknown, but it has been shown to be related to a number of different cancer types." (PMID 34149798, 2021). "Much less is known about SWI/SNF subunits BRD7 and BRD9 when it comes to their roles in cancer." (PMID 34298819, 2021). "With poor outcomes for patients with advanced stage cancer and the development of resistance to existing therapies, BRD9 may have utility along the PCa clinical pathway as a biomarker and a therapeutic target." (PMID 34944438, 2021). "Furthermore, we also note that BRD9 inhibition (or degradation) is an attractive therapeutic aim for the treatment of several cancers." (PMID 34397140, 2021). "Since EMT was critical for the metastasis of cancer cells, we explored whether BRD9 affected the EMT of HCC cells." (PMID 32908135, 2020).
cancer (continued). "A recent analysis of TCGA data from cBioPortal found that BRD9 was amplified in bladder cancer, lung squamous cell carcinoma, lung adenocarcinoma, esophageal carcinoma, and ovarian cancer, with several of these cancer types also displaying BAF53a amplification." (PMID 33143733, 2020). "This is in accordance with our results of Gene Ontology, which reveals that BRD9 appears to be significantly associated with DNA replication and repair processes, particularly non-homologous end joining, implicated in cancer." (PMID 32276436, 2020). "In addition, inhibitor of BRD9, I-BRD9, acts synergistically with olaparib in HR-proficient cancer cells." (PMID 32457312, 2020). "However, the role of BRD9 and its cell-context dependency in other cancers and diseases still needs to be addressed." (PMID 31000698, 2019). "For BRD9, we indicated remarkable copy number amplifications across multiple human cancers." (PMID 31504061, 2019). "BRD9 protein levels were dramatically increased in all cancer/tumorigenic cells analyzed." (PMID 31000698, 2019). "Additionally, ACTL6A and BRD9 showed a border spectrum of genetic alterations in five different cancer types." (PMID 31504061, 2019). "Moreover, more and more studies suggested that BRD9 plays key roles in the proliferation of cancers." (PMID 31504061, 2019). "For example, 66.7% (42/63) of putative therapeutic target HAMPs are largely uncharacterized with limited indications about how these genes influence cell biology and cancer, although many of these understudied HAMPs are recurrently altered among cancers, such as BRD9, BRD1, BPTF, and ATAD2." (PMID 30760718, 2019). "In addition, based on the clinical data, the overexpression of ACTL6A and BRD9 reduced the survival time of patients in a set of cancers." (PMID 31504061, 2019). "We found that BRD9 mRNA was significantly upregulated in all cancer types studied." (PMID 30760718, 2019). "Additionally, the bioinformatics analyses were performed for two significantly amplified genes, ACTL6A and BRD9, to investigate their oncogenic roles in human cancers." (PMID 31504061, 2019). "Therefore, at least in these cancer types, the protein levels of both BRD9 and ACTL6A are increased with the increase of mRNA, and there is no any altered translocation has been discovered so far." (PMID 31504061, 2019). "We conclude that the BRD9 bromodomain is an attractive target for novel therapies in this cancer." (PMID 28714904, 2017). "Hence, BRD9 inhibitors and degraders are promising drugs for the treatment of diverse cancers." (PMID 38390898, 2024). "Therefore, although studies indicate that BRD9 inhibitors abrogate tumorigenicity in diverse cancer types, because the drugs differ in their selectivity, confirmation of the target via genetic depletion is crucial to understand drug mechanism in a particular cellular context." (PMID 38390898, 2024). "The regulatory functions of BRD9 may be impaired by cancer, such as MM." (PMID 39162964, 2024). "We could confirm mis-splicing and downregulation of BRD9 in SF3B1-mutated cancers, but neither mis-splicing nor downregulation of BRD9 was detected for ASB-CLL." (PMID 36266272, 2022). "Moreover, BRD9–ZINC2036848 complex interactions were reasserted during 100 ns MD simulation, which indicated that ZINC2036848 might be used as a potent antagonist towards BRD9 in cancer therapeutics." (PMID 36362300, 2022). "Therefore, compared to ACTL6A, BRD9 could be a better choice for us to develop the treatment of cancers." (PMID 31504061, 2019). "Finally, given that many HAMPs with high scores are understudied genes (e.g., BRD9), the overall recurrent score may also be used to prioritize the genes for basic biological studies in context of cancer." (PMID 30760718, 2019). "Therefore, we hypothesized that the overexpression of BRD9 might also receive signaling from embryonic stem cells and induce a metastatic stem-like profile in cancer cells." (PMID 31504061, 2019).
cancer (continued). "To determine whether the increased copy number of ACTL6A and BRD9 led to an increase in their expression levels, we acquired two pan-cancer boxplots regarding the difference of these two genes expression between normal and tumor tissues from Tumor IMmune Estimation Resource (Timer)." (PMID 31504061, 2019). "For example, BRD9 shows highest overall recurrent score among HAMPs (e.g., focally amplified in nine cancer types), strongly suggesting that targeting BRD9 by small molecular inhibitors may be a novel treatment strategy with wide clinical application for cancer therapy." (PMID 30760718, 2019). "The amplification of BRD9 may play a significant role in cancer." (PMID 31504061, 2019). "Drugs with higher potency and varying selectivity for either BRD9 and/or BRD7 have since been developed and tested for their anti-cancer effects." (PMID 38390898, 2024). "Especially BRD9 and ACTL6A show a high amplification frequency across multiple cancers, highlighting their oncogenic potential." (PMID 33941852, 2021). "In particular, specific molecules able to interfere with the activity of BRD9, one of the “reading” subunits contained in human SWI/SNF, prevent gene transcription and expression, reducing the rate of cancer proliferation." (PMID 34885774, 2021). "This technology was applied to target BRD9, and the developed PROTACs dBRD9 and VZ185 were much more effective in treating SMARCB1-mutant cancers than their parent inhibitor BI-7273." (PMID 33941852, 2021). "In summary, we clarified that BRD9 as a DDR factor facilitates HR through regulating RAD54–RAD51 complex, which in turn contributes to the chemoresistance of cancer cells." (PMID 32457312, 2020). "BRD9 is a subunit of the human BAF (SWI/SNF) nucleosome remodeling complex and has emerged as an attractive therapeutic target in cancer." (PMID 33115433, 2020). "One of the first selective inhibition studies focused on BRD4, a BRD9 paralog and BRD-containing protein family member with epigenetic mediatory activities and known roles in cancers, including chronic lymphocytic leukemia and human squamous carcinoma." (PMID 33143733, 2020). "In our study, higher mRNA and protein expressions of BRD9 were found in HCC, and mRNA expression of BRD9 was significantly correlated with cancer stages and tumor grades." (PMID 32927435, 2020). "Among 23 types of human cancers, HCC tissues showed an obvious elevation in BRD9 expression, compared with the corresponding normal tissues." (PMID 32908135, 2020). "To corroborate and strengthen the needed involvement of BRD9 in AML, we addressed its molecular role in cancer by mass spectrometry (MS)-based quantitative interaction proteomics." (PMID 31000698, 2019). "By targeting BRD9, we provided evidence that BRD9 regulates AML cancer cell proliferation and tumorigenicity, indicating its proto-oncogenic role in transformed blood cells." (PMID 31000698, 2019). "Among the recurrent genomic events, those in BRD9, EP300, ATAD2, HDAC4, PRBM1, BRD4, and BRD1 were observed in the highest numbers of cancer types (nine, eight, eight, eight, seven, seven, and seven, respectively)." (PMID 30760718, 2019). "For example, the BRD proteins BRD9, BRD4, and ATAD2 were focally amplified in multiple cancer types and their increased copy numbers were significantly, positively correlated with higher mRNA expression levels." (PMID 30760718, 2019). "The inhibition of Brd9 impairs the activity of TGF-β pathway in both hESCs and cancer cells." (PMID 39730061, 2024). "In addition, these studies revealed that eIF5A, BRD9, XRCC1, CYP1A1, and CRABP2 were miR-486-3p-regulated cancer-promoting genes in NSCLC cells." (PMID 37508549, 2023). "Therefore, we focused our attention on three genes coding for bromodomain-containing proteins (BAZ2A, BAZ2B, and BRD9) that were all expressed in paclitaxel-resistant SW1736 and 8505C cancer cell lines." (PMID 36983070, 2023). "SMARCD3, BRD9, JDP2, were also reported to be a oncogene role in some cancer." (PMID 36506326, 2022).
cancer (continued). "Previously, focal amplifications of BRD9 and ACTL6A have been identified and their overexpression may correlate with unfavorable clinical outcomes in a set of cancers." (PMID 34598711, 2021). "In cancers like AML and SqCLC, the apparent dependence of these cancer types on BRD9 may be a viable avenue for investigations into disease progression and treatment." (PMID 33143733, 2020). "Other sarcoma cell lines do not show this dependency on BRD9 which makes it a specific target in cancers with cBAF perturbations." (PMID 30898143, 2019). "Although the role of BRD7 in cancer has been extensively studied, the biological function and involvement in human malignancies of its close homolog BRD9 has not yet been elucidated." (PMID 31000698, 2019). "Among them, BRD9 and ACTL6A showed a high amplification frequency across multiple cancers." (PMID 31504061, 2019). "Therefore, perhaps the overexpression of BRD9 lead to more interaction between GBAF and enhancer of genome, which promote the transcription of some oncogenic genes, leading to the formation of cancer." (PMID 31504061, 2019). "Above all, we first indicated the common amplification of BRD9 and ACTL6A in cancers, which could be regarded as potential treatment targets in the future." (PMID 31504061, 2019). "First, we analyzed BRD9 mRNA expression and found that BRD9 mRNA expression levels were significantly higher in the BRD9-amplified tumors than in the non-amplified tumors across all nine cancer types." (PMID 30760718, 2019). "We also demonstrated that knockdown of EGFR, BRD9 and PPFIA1, which showed frequently copy-number gain at the genomic level, significantly inhibited cancer cell proliferation, indicating that these genes may play important oncogenic roles in ESCC." (PMID 28548104, 2017). "However, it is unclear whether BRD9 or BRD7, or both, were responsible for TP-472 anti-cancer effects." (PMID 38390898, 2024). "However, in those cancers where SMARCB1 is mutated the blockage of the bromodomain is not sufficient, requiring a complete degradation of BRD9, hinting to a need for structural disruption of ncBAF." (PMID 36810086, 2023). "Moreover, with the help of PROTACs developed to target BRD9 (dBRD9 and VZ185), it has been possible to verify that anti-cancer activity against AML might be achieved just by blocking the BRD9 bromodomain." (PMID 36810086, 2023). "Two cell lines, acute myeloid eosinophilic leukaemia (EOL-1) and malignant rhabdoid tumour (A-204), sensitive to BRD9 inhibition/degradation and dependent on an active BAF complex, were selected to study the impact of degrader-induced BRD7/9 degradation on the viability of cancer cells." (PMID 35702740, 2022). "Thus, the opposing functionalities of the closely related BRD7 and BRD9 proteins, as well as in SMARCA2/4, highlights the importance of understanding the roles of specific bromodomain-containing proteins in cancer biology in order to effectively develop new therapeutic strategies." (PMID 34298819, 2021). "However, despite this work in other cancers, BRD9 has not been well studied in PCa to date, with only one paper published in December 2020, which directly focused on BRD9 expression and inhibition in the disease." (PMID 34944438, 2021). "However, because of lacking related experiments, the specific mechanism of BRD9 in other cancers is still uncovered." (PMID 31504061, 2019). "BRD9 inhibition could promote CSC differentiation or decrease cellular plasticity by increasing the epigenetic barriers that are necessary for the cells to dedifferentiate from nonstem cancer cells to CSC." (PMID 37739089, 2024). "Interestingly, BRD9 is negatively correlated with PIK3CA; its correlation with KRAS is non-uniform, though it has been shown that BRD9 may mediate a PI3KCA-KRAS mutant oncogenic cancer phenotype." (PMID 34944438, 2021).